UPP1 (uridine phosphorylase 1)
Description:
Catalyzes the reversible phosphorylytic cleavage of uridine to uracil and ribose-1-phosphate which can then be utilized as carbon and energy sources or in the rescue of pyrimidine bases for nucleotide synthesis. Shows broad substrate specificity and can also accept deoxyuridine and other analogous compounds (Probable).
Synonyms: UP; UPASE; UPP; UDRPASE
Tractability: Small molecule: a structure with a bound ligand is known; a high-quality ligand is known; it has a high-quality binding pocket; it belongs to a druggable protein family. PROTAC: ubiquitination databases record sites on it; its protein half-life has been measured; a small molecule that binds it is known.
Target class: Enzyme; Transferase
Gene: Protein-coding gene on chromosome 7 (48,088,628 to 48,108,736, forward strand). Ensembl gene ENSG00000183696.
Subcellular location (Human Protein Atlas): Nucleoplasm
Pathways (Reactome):
Metabolism: Pyrimidine catabolism; Pyrimidine salvage
Gene Ontology:
Molecular function: identical protein binding; uridine phosphorylase activity; catalytic activity; deoxyuridine phosphorylase activity; pentosyltransferase activity; thymidine phosphorylase activity
Biological process: uridine catabolic process; nucleobase-containing compound metabolic process; cellular response to glucose starvation; CMP catabolic process; dCMP catabolic process; dTMP catabolic process; dUMP catabolic process; nucleoside metabolic process; nucleotide catabolic process; UMP catabolic process; UMP salvage
Cellular component: nucleoplasm; cytosol; cytoplasm
Genetic constraint (gnomAD): Loss-of-function variants: 20 observed, 26.33 expected, observed/expected ratio (o/e) 0.76, 90% interval 0.53 to 1.1. The upper end of that interval is the gene's LOEUF score, 1.1, which puts it in group 4 of 6, group 1 being the genes least tolerant of losing a copy. Missense variants: 345 observed, 401.84 expected, observed/expected ratio (o/e) 0.86, 90% interval 0.79 to 0.94. Synonymous variants: 153 observed, 158.7 expected, observed/expected ratio (o/e) 0.96, 90% interval 0.84 to 1.1.
Homologues: Orthologues: chimpanzee UPP1 (100% identical), macaque UPP1 (82% identical), rat Upp1 (80% identical), mouse Upp1 (79% identical), guinea pig UPP1 (77% identical), pig UPP1 (77% identical), tropical clawed frog upp1 (70% identical), rabbit UPP1 (68% identical), dog UPP1 (64% identical), Drosophila melanogaster CG6330 (50% identical), Drosophila melanogaster CG3788 (46% identical), zebrafish upp1 (46% identical), and 4 more. Paralogues in human: UPP2 (62% identical).
Diseases named in the same sentence as UPP1 in open-access papers:
UPP1 is named in the same sentence as 52 diseases in open-access papers, as found by Europe PMC text mining. Sharing a sentence is not in itself a finding about the gene and the disease. The quoted sentences say what the papers report.
glioma (10 papers, 2020 to 2025). A benign or malignant brain and spinal cord tumor that arises from glial cells (astrocytes, oligodendrocytes, ependymal cells). "Research has also noted a relationship between methylation patterns at CpG sites targeting SMOC1, KCNA4, SLC25A21, and UPP1, and the molecular characteristics of glioma, such as IDH mutations and 1p/19q co‐deletions, which aligns with our findings." (PMID 40781854, 2025). "IDH mutation can promote CIMP in gliomas which explains the increased methylation in UPP1-associated probes, but our observation suggests that UPP1 methylation can also be associated with 1p/19q codeletion." (PMID 33498463, 2021). "In addition, when comparing the two groups defined by IDH mutation status, UPP1 expression was found to be significantly upregulated in IDH wildtype glioma than that in IDH mutant type across different WHO grades in both datasets, except for WHO grade I in CGGA." (PMID 32583596, 2020). "employed a machine learning-based approach and identified UPP1 as a critical oncogene involved in tumorigenesis and immune evasion in gliomas." (PMID 40777122, 2025). "To study the effects of DNA methylation on c-Jun binding, we determined binding of the nuclear extracts from NHA, WG12, LN18 and LN229 glioma cells to unmethylated and methylated UPP1 promoter region using EMSA." (PMID 36850002, 2023). "We demonstrated that binding of c-Jun to VIM and UPP1 promoters is stronger in human glioma cells derived from GIV versus GII tumors." (PMID 36850002, 2023). "Our analysis aligns with the previous studies where UPP1 gene expression was greatest in glioma Grade IV samples with demethylation at the CpG site captured by cg16270885 and correlates with lower patient survival." (PMID 33498463, 2021). "Gene expression of SMOC1, KCNA4, and SLC2521 declined as patient glioma grade increased while UPP1 gene expression showed a positive relationship with tumor grade." (PMID 33498463, 2021). "CpG site of UPP1 demethylate as glioma grade increases while the remaining genes, SMOC1, KCNA4, and SLC25A21, methylate along with higher tumor grade." (PMID 33498463, 2021). "To address the role of UPP1 in glioma, we carried out this bioinformatic analysis based on the two large cohorts of glioma samples from CGGA and TCGA project." (PMID 32583596, 2020). "In both CGGA and TCGA dataset, the expression level of UPP1 showed a significantly positive correlation with WHO grade of glioma, suggesting that higher UPP1 level was paralleled with higher malignancy in glioma." (PMID 32583596, 2020). "In this bioinformatics analysis, UPP1 was identified as a novel molecule that was supposed to play a vital role in glioma." (PMID 32583596, 2020). "Mesenchymal subtype, the most aggressive type of glioma, showed universally higher expression level of UPP1 than that of other less malignant subtypes in both datasets." (PMID 32583596, 2020). "Taken together, UPP1 played an oncogenic role in glioma via suppressing tumor‐related immune response." (PMID 32583596, 2020). "In conclusion, UPP1 was significantly upregulated in glioma, especially in glioblastoma, and exhibited considerable predictive value for prognosis." (PMID 32583596, 2020). "Additionally, UPP1 was found positively correlated with various immune checkpoint members, underscoring its potential oncogenic role in glioma by modulating the tumor-related immune response." (PMID 38331898, 2024). "It indicated that UPP1 expression is positively correlated with the grade of gliomas." (PMID 34568031, 2021). "Only one bioinformatic analysis of UPP1 expression in gliomas has been published." (PMID 34568031, 2021). "Furthermore, in GBM, the most aggressive type, UPP1 participated in the regulation of apoptosis, corresponding to active anti‐apoptosis characterization of GBM, which further validated the oncogenic effect of UPP1 in glioma." (PMID 32583596, 2020).
glioma (continued). "Finally, Kaplan‐Meier curves revealed that higher UPP1 indicated significantly shorter survival for glioma patients." (PMID 32583596, 2020). "Subsequent ROC analyses revealed that UPP1 may function as an effective biomarker for identification of mesenchymal subtype glioma, with the AUC of 92.1% in CGGA and 88.0% in TCGA." (PMID 32583596, 2020). "The prognostic value of UPP1 for glioma was investigated based on Kaplan‐Meier survival analysis." (PMID 32583596, 2020). "UPP1 expression level was positively correlated with WHO grade of glioma." (PMID 32583596, 2020). "High expression level of UPP1 predicts poor prognosis in glioma." (PMID 32583596, 2020). "According to median UPP1 expression, glioma patients were divided into two groups in each dataset." (PMID 32583596, 2020). "However, further study is needed to elucidate the function of UPP1 in the tumorigenesis of glioma." (PMID 32583596, 2020). "When GII/GIII-IDHmut gliomas were compared to GIV gliomas, significant differences of DNA methylation in the promoters of S100A2, RAB36, RIN1, UPP1, and VIM were found." (PMID 36850002, 2023). "We verified the binding and presence of c-Jun at two candidate gene promoters (VIM, UPP1) in glioma cells and found a stronger binding in GBM-derived cells in comparison with cells derived from the low grade glioma." (PMID 36850002, 2023). "This indicated that UPP1‐related biological process were more involved in IDH wildtype, representing a more aggressive and malignant type of glioma." (PMID 32583596, 2020). "Thus, we enrolled and analyzed glioma samples from Chinese Glioma Genome Atlas (CGGA) dataset and The Cancer Genome Atlas (TCGA) dataset, aiming at characterizing UPP1 expression in glioma molecularly and clinically." (PMID 32583596, 2020). "This suggested that UPP1 may serve as a negative prognosticator in glioma." (PMID 32583596, 2020).
pancreatic cancer (8 papers, 2020 to 2025). "Recently, it has been reported that ribose derived from uridine by UPP1 can overcome the growth defects induced by glucose deficiency in pancreatic cancer and that high UPP1 expression predicts poor outcomes in patients with pancreatic cancer." (PMID 40804482, 2025). "This includes studies in pancreatic cancer, where UPP1-dependent production of ribose-1 phosphate was found to fuel central carbon metabolism in nutrient-deprived conditions." (PMID 40702342, 2025). "In the present study we have utilised GEMMs to study how UPP1 contributes to cancer progression in both mammary and pancreatic cancer." (PMID 40702342, 2025). "We have found that there are differences in the roles played by UPP1 in the progression of mammary and pancreatic cancer." (PMID 40702342, 2025). "A metabolite screen of pancreatic cells shows that pancreatic cancer cells metabolize uridine-derived ribose via UPP1, supporting redox balance, survival and proliferation." (PMID 37198494, 2023). "Importantly, in human cancer patients, increased expression of UPP1, in tumour core biopsies, consistently correlated with decreased survival in breast, colon and pancreatic cancer." (PMID 40702342, 2025). "To determine whether UPP1 supports tumour growth in vivo, we generated two independent models of UPP1-KO in the syngeneic mouse pancreatic cancer lines MT3-2D and KPC 7940b." (PMID 37198494, 2023). "To determine if UPP1 influenced metastasis in another cancer type that we have found to display increased levels of Upp1 and circulating uracil, we assessed the influence of Upp1 knockout on disease progression in the KPC GEMM of pancreatic cancer." (PMID 40702342, 2025). "We selected the marker genes (ADM, ERO1A, ENO2, BNIP3, and UPP1) of CAF-C2 to detect their expression in human pancreatic CAF-stellate cell (CAF118), human pancreatic cell (HPC-Y5), and human pancreatic cancer cell line." (PMID 36544710, 2022). "In pancreatic cancer, deletion of Upp1 in KPC mice also did not significantly influence primary tumour growth, but local invasion of PDAC was significantly decreased in the absence of Upp1." (PMID 40702342, 2025).
thyroid cancer (7 papers, 2019 to 2024). "In this review, clinicopathologic characteristics associated with higher UPP1 expression in thyroid cancer has been discussed." (PMID 31496029, 2019). "In conclusion, UPP1 gene could be a critical diagnostic, prognostic and predictive biomarker in thyroid cancer." (PMID 31496029, 2019). "In thyroid cancer, UPP1 was elevated in carcinoma tissue compared to adjacent tissue and was markedly associated with lymph node involvement." (PMID 36186123, 2022). "Emerging evidence indicates that the expression of UPP1 is associated with multiple malignant tumors, including colorectal cancer (CRC), breast cancer, pancreatic cancer, and thyroid carcinoma." (PMID 36186123, 2022). "We further tested the impact of UPP1 silencing on 5‐FU chemo sensitivity in thyroid cancer cell lines." (PMID 31496029, 2019). "In a word, there is a positive correlation between the UPP1 expression and thyroid cancer metastasis capacity." (PMID 31496029, 2019). "The significant upregulation of UPP1 in thyroid cancer tissues compared with normal thyroid tissues was revealed by our data and TCGA data." (PMID 31496029, 2019). "And colony‐forming assay, we found that down‐regulating the level of UPP1 expression significantly inhibits proliferation in thyroid cancer cell line (TPC and BCPAP)." (PMID 31496029, 2019). "In our study, we assessed the UPP1 expression in the TCGA and measured the levels of UPP1 in thyroid cancer tissues and corresponding normal tissues by RT‐qPCR (24 pairs)." (PMID 31496029, 2019). "The ROC curves for UPP1 expression to diagnose thyroid cancer in the TCGA and validated cohort both are >0.9 (AUC was 91.1% (87.7%‐94.6%) in TCGA and 93.6% (87.2%‐99.9%) in validated cohort), which usually indicate high accuracy." (PMID 31496029, 2019). "Although we discovered the potential diagnostic value of UPP1 in thyroid cancer and related EMT, the specific mechanisms of UPP1 in thyroid cancer remain to be further investigated." (PMID 31496029, 2019). "The results showed that knock‐down of UPP1 induced increased apoptosis in thyroid cancer cells (TPC, BCPAP), especially late‐stage apoptotic cells, compared with corresponding Si‐NC cell lines." (PMID 31496029, 2019). "Analysed the date of patients with thyroid cancer from TCGA, tumours were significantly smaller, and tumour capsule invasion was seen less frequently in patients with UPP1 low‐expression group." (PMID 31496029, 2019). "In this study, we reports UPP1 was significantly upregulated in thyroid cancer tissues compared with normal thyroid tissues in TCGA dates and our verified dates." (PMID 31496029, 2019). "High expression of UPP1 was reported in breast cancer and thyroid cancer cells." (PMID 35073659, 2024). "We found UPP1 expression is significantly upregulated in thyroid cancer." (PMID 31496029, 2019). "Our findings indicate that UPP1 might be a biomarker of thyroid cancer and may act by regulating epithelial‐mesenchymal transition (EMT)." (PMID 31496029, 2019). "This seems to suggest that the UPP1 gene is a valuable biomarker for thyroid cancer." (PMID 31496029, 2019). "In this article, we investigate the function of UPP1 expression in thyroid cancer." (PMID 31496029, 2019). "Does that mean the thyroid cancer with lower expression of UPP1 would lower sensitive to 5‐FU?" (PMID 31496029, 2019). "Moreover, we demonstrated that cell proliferation, migration and invasion were significantly inhibited when UPP1 expression was down‐regulated in thyroid cancer cell lines." (PMID 31496029, 2019). "In this article, we will clarify the expression and effect of UPP1 in thyroid cancer." (PMID 31496029, 2019). "But the function of UPP1 is still unknown in thyroid cancer." (PMID 31496029, 2019). "However, we found the high expression of UPP1 in thyroid cancer." (PMID 31496029, 2019).
thyroid cancer (continued). "It suggests that UPP1 could be a potential marker to monitor thyroid cancer in a variety of thyroid cancer cell lines, and the expression of UPP1 also performs a higher level compared with normal cells line (compared with HTORI‐3, TPC, P < .05; BCPAP, P < .01)." (PMID 31496029, 2019). "Results of our study shared down‐regulated UPP1 expression in thyroid cancer cell line can inhibit cell metastasis by EMT and do not affect the sensitivity to 5‐FU by EMT." (PMID 31496029, 2019).
breast cancer (6 papers, 2019 to 2025). A primary or metastatic malignant neoplasm involving the breast. "The ability of UPP1 to influence the progression of mammary cancer was therefore assessed by comparing primary tumour development and incidence of lung metastasis in MMTV-PyMT:Upp1+/+ mice to that in MMTV-PyMT:Upp1−/− mice." (PMID 40702342, 2025). "Knockout or inhibition of UPP1 in mice with mammary tumours increases T-cell numbers and reduces fibronectin content in the lung, and decreases the proportion of mice that develop lung metastasis." (PMID 40702342, 2025). "Mammary tumours increase expression of adhesion molecules on the neutrophil surface, in a UPP1-dependent manner, leading to decreased neutrophil motility in the pre-metastatic lung." (PMID 40702342, 2025). "We found that 4T1 breast cancer increased Upp1 expression in the liver, implying that there is an increased flux of uridine to uracil in the 4T1 breast cancer-bearing condition." (PMID 35705545, 2022). "Uridine phosphorylase 1 (UPP1) is a protein‐coding gene and has been detected that UPP1 was the higher expression in many solid malignancies, just as head and neck cancers, breast cancer, compared with paired normal tissue." (PMID 31496029, 2019). "Taken together, these data suggest that the increased numbers of IL-2+ CD8+ T cells in the lungs of mammary tumour-bearing Upp1−/− mice may be accounted for by the reduced ability of neutrophils from MMTV-PyMT Upp1−/− mice to suppress T-cell proliferation." (PMID 40702342, 2025). "Furthermore, the expanded T-cell population in the lungs of mammary tumour-bearing Upp1 knockout mice express IL-2, a cytokine that actively promotes T-cell proliferation." (PMID 40702342, 2025). "Importantly, no increase in cell surface αM integrin was detected in lung neutrophils from mammary tumour-bearing mice treated with BAU to inhibit UPP1 activity." (PMID 40702342, 2025). "Collectively, these data suggest that mammary tumours can influence the surface expression of molecules such as αM integrin in a UPP1-dependent manner, and the consequent cell surface availability of αM integrin affects the migratory capacity of neutrophils in the pre-metastatic lung." (PMID 40702342, 2025). "Indeed, mice which lack the gene for Upp1 (Upp1−/− mice), display increased levels of uridine and decreased levels of uracil in tissues and serum, whilst mammary tumours from MMTV-PyMT mice displayed reduced uracil, but unaltered uridine levels." (PMID 40702342, 2025). "Specifically, we show that a key aspect of pyrimidine metabolism (uridine phosphorylase-1 (UPP1)-catalysed phosphorolysis of uridine into uracil and ribose-1 phosphate) influences priming of the lung metastatic niche, and consequent metastasis of mammary cancer to this organ." (PMID 40702342, 2025). "In the case of mammary cancer, UPP1 does not contribute to growth of primary mammary tumours, but is key to the establishment of lung metastases." (PMID 40702342, 2025). "In the absence of UPP1 expression/activity, we show that the number of T cells in the lungs of mice bearing mammary tumours increases." (PMID 40702342, 2025). "Importantly, in the absence of UPP1 the ability of mammary tumours to metastasise is reduced, and we thus highlight a specific role for UPP1 in the metastatic process." (PMID 40702342, 2025). "Importantly, we find that the ability of mammary cancer to metastasise to the lungs is reduced in the absence of UPP1." (PMID 40702342, 2025).
lung adenocarcinoma (6 papers, 2022 to 2025). A carcinoma that arises from the lung and is characterized by the presence of malignant glandular epithelial cells. "Tumour-specific UPP1 increases have also been associated with disease progression in lung adenocarcinoma." (PMID 40702342, 2025). "UPP1 is also known to be upregulated in several malignancies, including lung adenocarcinoma, bladder, gastric, and colorectal cancers." (PMID 40358702, 2025). "The steady-state level of UPP1 mRNA is positively correlated with the poor prognosis of patients with multiple types of malignant tumors, including breast cancer, lung adenocarcinoma and oral squamous cell carcinoma." (PMID 40804482, 2025). "In lung adenocarcinoma, UPP1 knockdown via shRNA reduced the protein levels of ENO1 and LDHA in H292 and H1975 cells, whereas overexpression of UPP1 restored the suppression of lactate production, glucose uptake and ENO1/LDHA protein levels induced by 2-deoxy-d-glucose in H1299 cells." (PMID 40804482, 2025).
colorectal cancer (5 papers, 2003 to 2025). A primary or metastatic malignant neoplasm that affects the colon or rectum. "In addition, CB-839 upregulated the expression of UPP1 in various transplantation tumor models, strengthening the inhibitory effect of 5-FU on PIK3CA-mutant colorectal cancer." (PMID 38385072, 2024).